IL6 (interleukin 6)
Diseases named in the same sentence as IL6 in open-access papers (continued):
Sharing a sentence is not in itself a finding about the gene and the disease.
COVID-19 (continued). "Persisting and even further elevation of IL-6 levels in the long-term post-COVID might be an alarming signal of a persistent COVID-19-induced inflammatory state." (PMID 36835948, 2023). "IL-6 is a crucial cytokine that is notably increased in COVID-19-infected patients." (PMID 37680629, 2023). "Additionally, in COVID-19 patients, serum levels of IL-6, TNF-α, IL-8, and IL-10 were negatively correlated with lymphocyte counts." (PMID 37654571, 2023). "Several patient variables related to serum IL-6 and COVID-19 severity have been examined." (PMID 37960722, 2023). "Previous studies have shown a correlation between IL-6 levels and COVID-19 severity." (PMID 37568870, 2023). "Furthermore, several inflammatory biomarkers of COVID-19, such as TNF-α, IL-6, ACE2, and NLR, were shown to be highly associated with ROS and RNS concentrations in patient sera." (PMID 37240319, 2023). "Notably, during SARS-CoV-2 infection, patients with COVID-19 experienced increased secretion or production of IL-6 and IL-8 and an overall decrease in CD4+ and CD8+, as well as T cells." (PMID 38322760, 2023). "Based on hsTnI levels, COVID-19 patients were divided into two groups to analyze the level of IL6." (PMID 37564653, 2023). "Proinflammatory cytokines involved in COVID-19 and “long COVID-19,” such as IL-1 and IL-6, may contribute to the pathogenesis of fibromyalgia and low-grade fever." (PMID 37089610, 2023). "In this study blood levels of sP2X7R measured at the time of diagnosis at hospital admission in a cohort of COVID-19 patients were correlated to (a) several markers of inflammation and tissue damage, (b) sNLRP3, IL-6, IL-10, and IL-1β levels, and most importantly, (c) disease progression." (PMID 37215142, 2023). "Other biomarkers that have been associated with COVID-19 and cardiovascular complications include interleukin-6 (IL-6), C-reactive protein (CRP), and ferritin, which are markers of inflammation and have been linked to a hyperinflammatory response in severe COVID-19 cases." (PMID 37568870, 2023). "The inclusion of Delirium and IL6 as additional prognostic indicators in the scoring systems enhanced their predictive performance, specifically in determining in-hospital mortality among COVID-19 patients." (PMID 37329431, 2023). "The comparison analysis by post hoc test among the groups in this study based on the biomarkers showed that CRP, ferritin, ESR, and IL-6 are significantly changed in COVID-19 patients and could be a promising biomarker among the patients." (PMID 37363608, 2023). "Additionally, several studies highlighted that inflammatory cytokines such as IL-6 and IL-10 were present in highest levels in severe COVID-19 (acute) compared to moderate/mild or HC." (PMID 37228606, 2023). "Other inflammatory parameters that have been tested for COVID-19 severity and mortality risk assessment in adults such as IL-6, LDH, and procalcitonin were not routinely ordered across our pediatric institutions and therefore not included in analysis." (PMID 37425266, 2023). "The present study proposed that modulation of the inflammatory immune response via one of the following targets: IL-6, IL-17, and IL-2 could improve clinical outcomes of COVID-19 patients when compared to the SOC treatment." (PMID 37075454, 2023). "On the other hand, SARS-CoV-2 infections induce IgG4 production, and high serum IgG4 concentrations (>700 mg/dL) were linked to a considerably higher 30-day death rate and were significantly correlated with IL-6 levels, a known forecaster of COVID-19-related mortality." (PMID 37759738, 2023). "A few studies have reported that treatment with IL-6 antagonist tocilizumab could lead to a decrease in ferritin levels in severe COVID-19 cases." (PMID 37046952, 2023). "Moreover, the proposed aptamer-functionalized SiNW-FET detection range is sufficient to measure IL-6 expression levels in COVID-19-infected patients and distinguish between mild and severe disease." (PMID 37571591, 2023).
COVID-19 (continued). "Interestingly, COVID-19 patients who develop severe disease have a complex maladapted immune profile that is accompanied by an increase in cytokines, such as IL-6, along with higher type-1 (e.g. IL-12) and type-2 cytokine (e.g. IL-5) levels." (PMID 37705107, 2023). "This study concludes that IL-6, ARDS, and AKI are risk factors for death in children with COVID-19." (PMID 37889917, 2023). "Elevated IL-6 has been acknowledged as important marker for complicated courses of COVID-19." (PMID 36631778, 2023). "Consequently, we found that patients with severe COVID-19 with IL-6 values at 24 h ≥ 11, NLR values at 24 h ≥ 22, and NLR values at 72 h ≥ 14 were 8.3, 3.8, and 3.8 times more likely to die at 28 days, respectively." (PMID 36675573, 2023). "The moderate form of COVID-19 registered significantly higher values of IL-6, CRP, and IgG." (PMID 36838284, 2023). "However, we corrected for gender, BMI and IL-6 levels, which are all reported to have an impact on outcome during severe COVID-19 reducing confounding." (PMID 37582864, 2023). "Likewise, when compared with the non-PASC group using four relevant cohorts from three studies, long COVID-19 patients had higher mean IL-6 levels (mean difference = 3.32 pg/ml, 95% CI = 0.22–6.42 pg/ml, I2 = 88%, P = 0.04)." (PMID 37095536, 2023). "Additionally, tocilizumab is a recombinant humanized monoclonal antibody that inhibits the IL-6 receptor and has been used to reduce IL-6-mediated inflammatory responses in patients with severe COVID-19." (PMID 37654571, 2023). "Serum IL-6 levels are correlated with the stage of COVID-19 as well as respiratory failure." (PMID 36769328, 2023). "Elevated levels of IL-6 increase C-reactive protein synthesis and disrupt T-cell regulation and macrophage response, making it an important biomarker in determining the severity of COVID-19." (PMID 37457959, 2023). "It has been established that increased plasma levels of cytokines and chemokines, IL-6 in particular, are significantly higher in severe than in mild to moderate disease allowing to predict COVID-19 severity and survival and correlate with the harshness of the disease." (PMID 37767093, 2023). "Thus, it should be noted that higher levels of IL-6 and lower levels of IL-10 are related to COVID-19 severity and worse prognosis." (PMID 36914565, 2023). "Additionally, the IL-1 (Anakinra), and the IL-6 (Tocilizumab) receptor blockers showed a significant improvement in COVID-19-infected individuals, which supports the COVID-19 "cytokine storm" response theory." (PMID 38313184, 2023). "Our unpublished data indicate elevated IL-6 levels in some COVID-19 patients." (PMID 37766091, 2023). "Since high levels of IL-6 in blood can indicate inflammation, infection, cardiovascular diseases, or autoimmune disorders, IL-6 can also be used as a biomarker for disease progression in COVID-19 patients." (PMID 37896795, 2023). "Therefore, it is possible that IL-6 produced by muscle tissue with fatty degeneration affect disease course of COVID-19 to some extent." (PMID 37506083, 2023). "In the severe COVID-19 group, more patients (n = 33, 97.06%) had IL-6 levels above the cut-off." (PMID 38099004, 2023). "In the pre-COVID-19 data set, IL1β, IL6, and TNF were found to have decreased in both groups." (PMID 37546047, 2023). "Other studies emphasize this connection by showing positive correlation between elevated IL-6 level and increased severity of COVID-19, such as exacerbated respiratory failure, hypercytokinemia and rapid progression to acute respiratory distress syndrome (ARDS)." (PMID 37005767, 2023). "Similar associations were observed between risk phenotypes of diabetes and severity of COVID-19, with some new evidence on existing COVID-19 vaccination status (0.32 [0.26, 0.38], n=3), pre-existing hypertension (1.23 [1.14, 1.33], n=49), neuropathy and cancer, and high IL-6 levels." (PMID 37204441, 2023).
COVID-19 (continued). "Several signaling pathways are intertwined by the activity of TNF-α, IL-6, and L-10, which may contribute to triggering sudden mucus hypersecretion along with other mediators of the COVID-19 cytokine storm." (PMID 38193087, 2023). "Additionally, IL-6 levels were shown to be elevated in patients with severe COVID-19 and decreased during the recovery phase of COVID-1930." (PMID 37612352, 2023). "Owing to its central role in COVID-19 pathogenesis, IL-6 could be a very attractive target for Covid-19 immunomodulation therapies." (PMID 37075454, 2023). "IL-6 receptor antagonists have demonstrated benefits in reducing mortality among high-risk patients in systematic reviews and meta-analyses; thus, targeting IL-6 or its receptors could be a promising therapeutic option for severe COVID-19 cases." (PMID 37533131, 2023). "The high risks of developing severe COVID-19 are strongly associated with inflammatory markers such as procalcitonin (PCT), serum ferritin, erythrocyte sedimentation rate (ESR), C-reactive protein (CRP), and interleukin-6 (IL-6)." (PMID 36837428, 2023). "IL-6, which is a practical biomarker of systemic inflammation and adverse outcomes of acute COVID-19, may serve as a useful predictor of LC after a time window of 4-weeks post-infection, informing on the “early stage” of LC." (PMID 37445634, 2023). "Reduced levels of T cells and their function in severe COVID-19 may be due to lower levels of IL-6, which is secreted by T cells, macrophages, endothelial cells, fibroblasts and monocytes." (PMID 38137381, 2023). "IL-6 plays an important role both in periodontitis and COVID-19." (PMID 36769328, 2023). "Notably, a single subcutaneous injection of the monoclonal PCSK9 antibody evolocumab reduced the need for intubation and/or mortality and lowered serum interleukin (IL)-6 in patients with severe COVID-19." (PMID 37515197, 2023). "In addition, a number of research studies have used the Meso Scale Discovery (MSD) biomarker platform to measure IL-6 levels and identify thresholds to predict clinical outcomes in COVID-19." (PMID 37650680, 2023). "Moreover, in patients with severe COVID-19, markedly elevated levels of inflammatory markers such as IL-1, IL-6, and TNF-alfa have been detected." (PMID 36830905, 2023). "Thus, the use of IL-6 inhibitors to treat COVID-19 has been attempted, with a success rate of approximately 32%." (PMID 36914565, 2023). "Increased cytokine levels (such as interleukin 6 and ferritin levels of COVID-19 patients)." (PMID 37600568, 2023). "In this regard, the consequences of IL-6 blockade in COVID-19 may vary depending on the infection stage and the host’s immune status." (PMID 37818368, 2023). "Previously, we have also shown a decrease in the proportion of NKG2D+ NK cells in ICU and moderate patients with COVID-19, that via IL-6 could reduce the activity of NK cells by suppressing the expression of NKG2D." (PMID 37240393, 2023). "The Roche IL-6 levels were overlapping between COVID and non-COVID-19 patients." (PMID 37650680, 2023). "Furthermore, in COVID-19 patients with increased levels of IL-6, the frequency of exhausted T cells is elevated." (PMID 37654571, 2023). "COVID-19 patients’ blood profiles have been detected with a high level of IL-6." (PMID 37371870, 2023). "However, the value of IL-6 as a predictor of the outcome in critically ill patients with COVID-19 is still controversial." (PMID 36675573, 2023). "The elevation of certain cytokines in COVID-19 patients (i.e., IL-6, IL-1β, and IFN-γ), may also be due to the presence of the virus or its remnants in PASC patients." (PMID 36947108, 2023). "Indeed, many cytokines are transactivated via the NF-κB signaling pathway, including those implicated previously in the inflammatory storm that accompanies severe COVID-19, such as IL-1, IL-6, IL-8, TNF, and CXCL1033." (PMID 37225706, 2023).
COVID-19 (continued). "Herein, we tested whether immunomodulation focusing on interleukin (IL)-6, IL-17, and IL-2, could improve the clinical outcomes of patients admitted with COVID-19." (PMID 37075454, 2023). "Interestingly, the post- COVID-19 cohort presented lower IL-6, IFN-γ, and TNF-α production after cell culture incubation with pathogenic stimulus." (PMID 37753077, 2023). "Moreover, IL-6 and MCP-1 are considered as the main risk factors related to mortality in hospitalized COVID-19 patients." (PMID 37034572, 2023). "Although some studies correlate cytokines such as IL-6 and IL-10 as predictors of COVID-19 severity, elevated IL-10 levels could act to moderate excessive inflammation even though it is not able to do so." (PMID 36969257, 2023). "Testing serum levels of interleukin-6 in children with COVID-19 could be useful to better understand the outcome of lung damage." (PMID 37889917, 2023). "The hyperinflammatory COVID-19 response is mediated, at least partially by the rapid proliferation and/or activation of immune cells and overproduction of pro-inflammatory cytokines, such as interleukin 6 (IL-6) and the tumour necrosis factor (TNF)." (PMID 36791125, 2023). "A beneficial effect of colchicine, an anti-inflammatory agent used to treat gout, viral pericarditis, and coronary heart disease could be expected in COVID-19 due to its indirect inhibition of IL-6." (PMID 37075454, 2023). "This may underlie our observation that HGF was inversely regulated with D-dimers and IL-6 and might reflect the coordinated sequelae of tissue injury and healing processes in severely affected COVID-19 patients." (PMID 37834869, 2023). "Numerous laboratory investigations, such as D-dimer, c-reactive protein (CRP), lactate dehydrogenase (LDH), ferritin, procalcitonin (PCT), and cytokine assays, especially interleukin-6 (IL-6), have been investigated for their prognostic and therapeutic role in COVID-19 patients." (PMID 38074058, 2023). "In-patients with moderate-to-severe COVID-19 who received single-strain probiotic Bifidobacterium boosters were found to have significantly shorter hospital stays, IL-6 level reductions, radiological lung improvements, and lower mortality rates relative to the non-probiotic group." (PMID 37841680, 2023). "Furthermore, elevated plasma levels of cytokine IL-6 have been shown to be a predictor of lung injury severity and mortality in COVID-19." (PMID 37632046, 2023). "It should be also mentioned that, although IL-6 is one of the main cytokines involved in COVID-19 inflammatory response, clinical trials with IL-6 receptor antagonists gave conflicting outcomes, and the effectiveness of IL-6 targeting approach remains to be established." (PMID 37649486, 2023). "It has been suggested that IL-6 levels are an important predictor of COVID-19 severity." (PMID 37753372, 2023). "The results of the present study suggest that low MBL levels may contribute to the increase in IL-6 in patients with severe COVID-19." (PMID 37138871, 2023). "COVID-19 disease progression is monitored using laboratory parameters such as lactate dehydrogenase, procalcitonin, C-reactive protein, and proinflammatory cytokines such as interleukin (IL)-6, IL-1β, Krebs von den Lungen-6 (KL-6), and ferritin." (PMID 37998327, 2023). "Anemic COVID-19 patients show the presence of high inflammatory markers like IL6 and CRP." (PMID 35849261, 2023). "Furthermore, IL-1, IL-6 and TNF-α produced by macrophages have been reported as pathogenic factors in the excessive inflammatory response in COVID-19." (PMID 37969879, 2023). "Moreover, in COVID-19 patients an extreme increase of pro-inflammatory cytokines and other factors has been observed, among which IL-6 and IFN-γ43." (PMID 36941368, 2023).
COVID-19 (continued). "Although cytokine storm and IL-6, in particular, are substantially increased in COVID-19 patients compared to other septic etiologies, and these are mechanistically upstream of numerous thrombogenic pathways, it is currently unclear which set of pathways are prominent in COVID-19." (PMID 36980393, 2023). "IL6, hepcidin and ferritin levels were positively correlated in a group of COVID-19 patients." (PMID 35849261, 2023). "Our study further supports this by showing that neonates with COVID-19 had lower levels of IL-6." (PMID 37416819, 2023). "This hypothesis is indirectly supported by a recent study that demonstrated that patients under anti-IL6 treatment showed lower antibody responses to COVID-19 mRNA vaccine." (PMID 36929282, 2023). "Elevated IL-1β and IL-6 responses have been associated with disease severity, suggesting that IL-1β and/or IL-6 may be key drivers of pathology in severe COVID-19." (PMID 37283924, 2023). "Patients with multiple comorbidities were the most vulnerable in the COVID-19 patients, and the dis-regulation of IL-6 and its receptor may have worsened the prognosis." (PMID 37887780, 2023). "Interestingly, following LPS and BzATP stimulation, we observed that PBMCs of COVID-19 patients significantly release more IL-1β and IL-6 compared to the control group." (PMID 37986089, 2023). "IL-6 and ferritin are known biomarkers for COVID-19 severity." (PMID 37515197, 2023). "In patients with moderate or severe COVID-19, serum levels of IL-6 are significantly elevated." (PMID 37654571, 2023). "In addition, the levels of pro-inflammatory cytokines, especially IL-6, were more highly elevated in severe cases of COVID-19." (PMID 36914565, 2023). "In the pathological study, it was shown that COVID-19 increased von Wildebrand factor (vWF) levels, increased platelet accumulation via IL-6-related pathways, and as a result of all, fatty liver cells, increased liver cell damage and increased ALT levels were observed." (PMID 37374367, 2023). "Also demonstrating this effect, IL-10 possibly regulated the Th17 profile in neonates of mothers with COVID-19 because the high levels of IL-6 detected generally act on the excessive increase of the Th17 profile." (PMID 36979888, 2023). "The detection range of the aptamer-functionalized SiNW-FET covered the concentration of IL-6, which could be used to predict fatal outcomes of COVID-19." (PMID 36679421, 2023). "Indeed, metformin has been shown to reduce the secretion of IL-6 and IL-1β by macrophages primed with the COVID-19 spike protein." (PMID 37886013, 2023). "Uncontrolled exploratory study showed that nebulized IFN-α2b in adult patients hospitalized with COVID-19 significantly reduced the duration of the detectable virus in the upper respiratory tract and duration of elevated levels of inflammatory markers (IL-6 and CRP) in the blood." (PMID 37240213, 2023). "IL-6 boosted in all forms of COVID-19, with a major increase in severe and critical patients." (PMID 36838284, 2023). "The level of IL-6 has also been reported to be elevated in complicated COVID-19 patients." (PMID 38152668, 2023). "In patients with severe and critical course of COVID-19 and with high blood viral excessive type I IFN response causes activation of NFκB-related inflammatory response associated with increased TNF-alpha and IL-6 synthesis." (PMID 37753372, 2023). "While IL-6 augmentation enhances the predictive power of clinical scores, delirium alone enhances the performance of COVID-19 clinical scores and may offer a faster and more cost-effective approach compared to measuring IL-6 levels." (PMID 37329431, 2023). "One characteristic of severe COVID-19 cases is the fast deterioration of the symptoms 1–2 wk after onset, accompanied by prolonged and elevated systemic pro-inflammatory cytokine levels, particularly interleukin (IL)-6, TNF, and IFNs." (PMID 37699657, 2023).